RNU4-35P (RNA, U4 small nuclear 35, pseudogene)
Gene: Small nuclear RNA gene on chromosome 6 (121,453,981 to 121,454,121, reverse strand). Ensembl gene ENSG00000199458.
Homologues: Paralogues in human: RNU4-13P (85% identical), RNU4-23P (82% identical), RNU4-67P (82% identical), RNU4-76P (82% identical), RNU4-7P (82% identical), RNU4-68P (81% identical), RNU4-58P (80% identical), RNU4-42P (79% identical), RNU4-45P (79% identical), RNU4-44P (79% identical), RNU4-84P (78% identical), RNU4-8P (78% identical), and 81 more.